MGMT (O-6-methylguanine-DNA methyltransferase)
Diseases named in the same sentence as MGMT in open-access papers (continued):
Sharing a sentence is not in itself a finding about the gene and the disease.
tumor (continued). "We further investigate MGMT’s emerging role as a molecular interlocutor within the tumor immune microenvironment (TIME), revealing its influence on the broader cellular ecosystem." (PMID 40895460, 2025). "The widespread adoption of hybrid imaging systems, cutting-edge tracers, and AI-driven radiomics has facilitated robust tumor characterization and the prediction of key biomarkers such as IDH mutations and MGMT promoter methylation." (PMID 40550035, 2025). "Its therapeutic benefit, however, strongly depends on the O6‐methylguanine‐DNA methyltransferase (MGMT) status of the tumour tissue." (PMID 40377133, 2025). "Further regression analysis of the statistical impact of MGMT-status, age and clinical status at time of recurrent diagnosis, as well as residual tumour volume on OS, PFS and KPS was performed." (PMID 41010757, 2025). "In parallel, single-cell epigenomic profiling enables the study of MGMT regulation at unprecedented resolution, revealing tumor heterogeneity and uncovering resistant subpopulations within tumors." (PMID 40895460, 2025). "Of importance, in vivo administration of α-syn also lowers MGMT, thus corroborating the protective role of α-syn against tumor development." (PMID 40108111, 2025). "MGMT is expressed in various normal tissues, however, MGMT expression has also been reported for several tumor types." (PMID 40244270, 2025). "A single dose of neoadjuvant nivolumab, ipilimumab and relatlimab increased the diversity, abundance and activation of TILs in the posttreatment tumor compared with the baseline tumor in newly diagnosed MGMT promoter unmethylated GBM." (PMID 40016450, 2025). "Of the n=91 patients, average age at diagnosis was 64 years (22–84 years), median age at diagnosis was 61.7 years, 30.8% had tumor biology where MGMT promoter was methylated, and 15.4% were considered frail." (PMID 41001028, 2025). "MGMT-Net kept on highlighting the tumor regions, which were of utmost biological relevance, during its prediction." (PMID 41007223, 2025). "MGMT is a pivotal DNA repair enzyme with profound implications for cancer biology, influencing tumor development, treatment response, and resistance to alkylating agents." (PMID 40895460, 2025). "MGMT methylation status is obtained by examining tumor tissue and is typically available to clinicians within 2–3 weeks of surgical resection once pathological analysis has been completed." (PMID 40428285, 2025). "Models based on radiomic analysis, using machine learning, can identify imaging features that correlate with the molecular status of a tumor, such as IDH1 mutation, MGMT promoter methylation, or EGFR amplification." (PMID 41465586, 2025). "When the MGMT promoter is highly methylated, gene expression is suppressed, and tumor cells become more sensitive to alkylating agents such as temozolomide." (PMID 41394878, 2025). "About 40%–50% of GBM patients have methylation of the MGMT gene promoter in their tumor, which silences MGMT expression." (PMID 41234540, 2025). "Integrating immunotherapy with MGMT modulation: Emerging evidence suggests that MGMT status influences tumor immune profiles." (PMID 40895460, 2025). "It is noteworthy and clinically relevant that we observed synergy between ONC201 and TMZ in H3K27M-mutated SF8628 cells and have also previously reported TMZ effects on immune killing by T-cells of high MGMT-expressing tumor cells." (PMID 40145650, 2025). "It promotes tumor migration and invasion by sponging miR-370-3p to regulate MGMT (O6-methylguanine DNA methyltransferase) expression while also facilitating TMZ resistance by transferring exosomal circWDR62 from TMZ-resistant to TMZ-sensitive cells." (PMID 40723354, 2025). "The ability of HGTX to induce oxidative stress in MGMT-proficient tumor cell lines was explored using the redox probe DCF-DA." (PMID 39997039, 2025).
tumor (continued). "N6022, a potent inhibitor of S-nitrosoglutathione reductase was used to extend the retention of nitrosylated MGMT in tumor cell culture and subcutaneous xenografts." (PMID 39997039, 2025). "These clinical data highlight the key role of MGMT in mediating resistance to TMZ across various tumor types." (PMID 41300971, 2025). "Evaluation of treatment tolerability, efficacy and effect on the immune response & identification of possible correlation between methylation status of MGMT and tumor response." (PMID 41208963, 2025). "HF3016 and HF2303 CSCs were derived from tumors with unmethylated and HF2927 CSC from a tumor with methylated MGMT promoter." (PMID 39919036, 2025). "In contrast, the group characterized by EGFR amplification and unmethylated MGMT had the highest rate of marginal recurrences (24.2%), potentially indicating a locally infiltrative tumor phenotype." (PMID 40722305, 2025). "Significant differences between non methylated and methylated MGMT tumors were observed in the total tumor/edema ratio ROI in both DL-models (DeepBraTumIA p = 0.02, Raidionics p < 0.01), and in the edema volumes extracted from DeepBraTumIA (p < 0.05)." (PMID 41476598, 2025). "Together, these insights highlight the dualistic nature of MGMT not only as a DNA repair factor but also as a modulator of immune dynamics within the tumor niche." (PMID 40895460, 2025). "Current methods for evaluation of MGMT promoter methylation status are limited to tumor tissue, requiring invasive biopsy or surgery, prompting the need for a liquid biopsy-based assay to expand and manage therapeutic interventions." (PMID 40250264, 2025). "As MGMT promoter methylation (MGMTpm) assessment requires tumor tissue, magnetic resonance imaging (MRI) is of interest for non-invasive prediction." (PMID 41476598, 2025). "Patient characteristics (Arm A vs B): median age 57 vs 49 years; male sex 70 vs 65%, gross total resection 61 vs 60%, tumor MGMT promotor methylation 39 vs 40%." (PMID 40800123, 2025). "For instance, studies reveal that inhibiting PARP activity in conjunction with the removal of MGMT allows for heightened sensitivity to TMZ by diminishing the tumor’s ability to repair alkylated DNA." (PMID 40895460, 2025). "Nrf2 also promotes detoxification pathways and regulates redox-sensitive DNA repair genes such as O6-methylguanine-DNA methyltransferase (MGMT), which contribute to tumor progression and therapeutic resistance." (PMID 40298811, 2025). "We evaluated clinical factors such as tumor grade, patient sex, patient age, IDH mutation status, 1p19q mutation status, MGMT promoter (MGMTp) methylation status, immune microenvironment status, and tumor mutation burden (TMB)." (PMID 40129966, 2025). "A higher ratio is derived from a larger total tumor or smaller peritumoral edema volume, which aligns with our findings showing larger peritumoral edema volume in MGMT-promoter methylated tumors." (PMID 41476598, 2025). "The unsatisfactory chemotherapeutic effect of TMZ is due to more than 50% of GBM patients being resistant to TMZ, mainly due to the high expression of O-6-methylguanine-DNA methyltransferase (MGMT), which alters methylation and preserves tumor cells." (PMID 40725030, 2025). "In contrast, although TMZ is effective in delaying tumor progression in vivo, its long-term efficacy is compromised by acquired resistance mechanisms, especially in tumors expressing high levels of MGMT." (PMID 40427146, 2025). "Methylation of the MGMT promoter (MGMTp) leads to transcriptional silencing, resulting in impaired DNA repair mechanisms and, consequently, increased tumor sensitivity to alkylating chemotherapy." (PMID 41346390, 2025).
tumor (continued). "The mRNA expression data available for 5348 PDX tumor samples representing 1056 distinct models in the NCI PDMR were used to correlate MGMT mRNA levels with promoter methylation status and with response to temozolomide in this study." (PMID 40458731, 2025). "We also discovered the effect of imipridones on suppressing MGMT expression to potentially sensitize tumor cells with unmethylated MGMT promoter to the anti-tumor effects of TMZ." (PMID 40145650, 2025). "Mice were euthanized and tumor samples were harvested for IHC analysis to examine Ki-67, PD-L1, MGMT, and β-catenin expression." (PMID 40809457, 2025). "The two main objectives of the suggested method are the segmentation of the tumor subregion and the radiogenomic categorization of the methylation status of the MGMT promoter." (PMID 41295120, 2025). "Third, due to data constraints, we were unable to incorporate additional tumor biomarkers (such as MGMT promoter methylation, TERT, etc.)." (PMID 41008886, 2025). "This aligns with findings from previous studies indicating that amino acid PET tracers, including FET, function independently of molecular tumor markers such as MGMT." (PMID 40994524, 2025). "Residual tumor volume mainly influences survival in the initial months following surgery, while MGMT promoter methylation and age remain significant predictors beyond this period." (PMID 41472359, 2025). "Traditionally, MGMT methylation status is assessed by sequencing the tumor tissue samples obtained from surgery or invasive biopsy, which is time-consuming and expensive." (PMID 39944537, 2025). "LP-184 has potent anti-GBM activity, including in TMZ-resistant and MGMT-expressing tumors, with effective brain and tumor penetration." (PMID 40628732, 2025). "The methylation state of the promoter of the MGMT gene is an essential indicator of tumor cells' response to TMZ chemotherapy." (PMID 40093343, 2024). "We then performed univariate CPH models for the well-known clinical prognostic factors of age, KPS, tumor size, extent of surgical resection, and MGMT promotor methylation status, as well as these six highly differentially expressed genes." (PMID 38612480, 2024). "CSA (p = 0.0022) and SI (p = 0.0015) both remained significantly associated with overall survival when adjusting for preoperative tumor volume, MGMT methylation status, age, EOR, and postoperative KPS." (PMID 39531176, 2024). "Tumor from 3 patients (3/12; 25%) harbored a methylated MGMT promoter and among those patients with sufficient tissue for analysis, 1 (1/8; 13%) tumor harbored mutant IDH." (PMID 39211521, 2024). "Patients with higher levels of MGMT had significantly poorer outcomes, with a hazard ratio (HR) of 1.88, after adjusting for age, sex, tumor size, tumor location, and T/N/M stage." (PMID 39041891, 2024). "Here, the unmethylated MGMT group demonstrated a trend towards increasing tumor burden over time, p = 0.03." (PMID 39001264, 2024). "Data from in vivo and in vitro studies across various tumor types have demonstrated that O6-4-BTG efficiently deactivates MGMT, resulting in a notable enhancement of tumor sensitivity to TMZ." (PMID 38254819, 2024). "Next, we comprehensively characterized the impact of MGMT promoter methylation on tumor transcriptome." (PMID 39618336, 2024). "In contrast, mifepristone reduces MGMT protein expression, potentially enhancing temozolomide efficacy by increasing temozolomide-induced DNA damage, apoptosis, and tumor cell death." (PMID 39768232, 2024). "If the MGMT gene is ‘silenced’, there is defective DNA repair leading to increased chemotherapy-related tumor cell death." (PMID 38791984, 2024). "MiRNA-181d directly impacts MGMT and serves as a tumor suppressor through its modulation of Bcl-2 and K-Ras." (PMID 39335591, 2024).
tumor (continued). "The MGMT protein expression within the tumor was found to exhibit a stronger effect on survival compared to the MGMG promotor methylation." (PMID 38639854, 2024). "MGMT promoter methylation results in lower MGMT DNA repair enzyme expression, making the tumor sensitive to alkylating agents like TMZ, and is predictive of improved survival." (PMID 39123366, 2024). "Of the 60 patients in whom the tumor MGMT promoter methylation status was known, 30 were methylated and 30 unmethylated." (PMID 39734810, 2024). "The inability to remove mutagenic adducts from guanine leads to DNA abnormalities and tumor growth when MGMT activity is lost." (PMID 38542081, 2024). "The addition of TMZ has shown a survival benefit, particularly for patients with MGMT promoter methylation, which is present in approximately 50% of tumor patients." (PMID 38229014, 2024). "Molecular biomarkers, including MGMT methylation, IDH1 and IDH2 mutations, and 1p/19q codeletion, are routinely used for tumor classification in clinical settings." (PMID 39768232, 2024). "Active MGMT expression enables tumor cells to mitigate the effects of temozolomide by facilitating DNA repair and promoting tumor growth." (PMID 38891882, 2024). "A recent study revealed that the methylation status of MGMT in extracellular vesicles in patient plasma is consistent with that in tumor tissue, and thus is also a usable biomarker to monitor GBM." (PMID 39273014, 2024). "In 165 patients with MGMT-methylated tumours, adding temozolomide increased overall survival by nearly six months (13.5 vs. 7.7 months, HR 0.53, 95% CI.38–0.73)." (PMID 39099691, 2024). "PXA‐like molecular alterations are another characteristic genetic alteration in these tumours, which harbour BRAFV600E mutations shown to favour MGMT hypermethylation." (PMID 38299304, 2024). "Approximately 40% of GBM patients harbor methylated MGMT, silencing expression in tumor cells, enhancing chemosensitivity and survival (progression-free survival (PFS) = 10.3 months, overall survival (OS) = 21.7 months)." (PMID 38224404, 2024). "We further compared clinical characteristics including the tumor grade, 1p/19q co-deletion, MGMT promoter methylation and TERT expression status among different clusters." (PMID 38971948, 2024). "The PED region offers additional insights into tumor growth, infiltration, and interactions with normal tissue, which are reflected in specific MRI imaging features, potentially indicating the MGMT promoter methylation status." (PMID 39716317, 2024). "Patients with tumours showing O6-methylguanine-DNA methyltransferase (MGMT) promoter methylation represent around 40% of newly diagnosed GBM." (PMID 38225549, 2024). "The clinical implication was that inhibiting the β‐Catenin‐MGMT functional axis via β‐Catenin knockdown or the use of selective antagonists restored tumor chemosensitivity to TMZ." (PMID 39041891, 2024). "Considering that two-thirds of these had a KPS ≥70%, and 6% an MGMT promoter-methylated tumor, the number of patients receiving combined radiochemotherapy followed by maintenance temozolomide was low." (PMID 38496908, 2024). "Patients with tumours showing MGMT promoter methylation represent around 40% of newly diagnosed GBM." (PMID 38225549, 2024). "Univariate Cox analyses indicated that the GS risk score, neoplasm grade, IDH1 mutation status, and MGMT promoter methylation were all significantly prognostic factors." (PMID 38819225, 2024). "This methylation is likewise sufficient for MGMT downregulation and chemosensitization, reflected by significant reductions of tumor cell survival in vitro." (PMID 38224404, 2024). "Adjuvant therapy of TMZ after RT is a safe therapeutic option, and its efficacy seems to be higher than that of RT alone, although it largely depends on individual factors such as MGMT promoter status and the histological type of the tumor." (PMID 39057168, 2024).
tumor (continued). "Specifically, we applied Cox to examine the effects of known factors in survival such as age, O6-methylguanine-DNA methyltransferase (MGMT) methylation status, extent of tumor resection (EOR), as well as the effects of sex and subtype on OS." (PMID 38418494, 2024). "When the MGMT promoter is methylated, the activity of the enzyme also decreases; however, with normal MGMT expression, the enzyme restores damage in tumor cells evoked by alkylating agents." (PMID 38396720, 2024). "Smaller tumor size, younger age, and methylated MGMT promoters are associated with improved survival., Future collaborative efforts are warranted to further distinguish GSM as an independent tumor entity and investigate GSM‐directed therapies." (PMID 39545524, 2024). "The primary strategy for developing a cancer-specific MGMT inhibitor involves modifying the inhibitor with tumor-targeting groups." (PMID 38254819, 2024). "In all the GSC lines, the methylation percentage of the MGMT promoter increased in comparison to the tumor bulks in which the cells originated." (PMID 38473989, 2024). "Of the 9 patients for whom tumor MGMT promoter methylation status was known, 8 (89%) harbored tumors with an unmethylated promoter." (PMID 38327681, 2024). "As expected, tumor grade, IDH1 mutation, MGMT promoter methylation, and Ki-67 expression were significantly associated with OS and PFS." (PMID 39049072, 2024). "Previous studies have shown that MGMT status is significantly correlated with certain imaging features on MR Images, such as tumor location, enhancement mode, necrotic tumor volume, and T2 / FLAIR hyperintense volume." (PMID 38992201, 2024). "Patients with O6-methylguanine-DNA-methyltransferase (MGMT) promoter methylated tumours have better outcomes from treatment with TMZ, compared to those with promoter unmethylated tumours." (PMID 38225549, 2024). "In another approach, the synthetic 3′-γ-folate ester of O6-benzyl-2′-deoxyguanosine not only increased MGMT inhibitory activity in tumor cells but also sensitized HT29 and A549 cells to BCNU cytotoxicity." (PMID 38254819, 2024). "Several previous studies have predicted MGMT methylation with visually assessed imaging features, tumor volume, texture features, and VASARI features." (PMID 38992201, 2024). "Epigenetic silencing of the MGMT gene by promoter methylation makes the tumor more sensitive to treatment with alkylating agents and has been associated with longer overall survival in patients with GBM who received TMZ chemotherapy." (PMID 38385046, 2024). "MGMT encodes a DNA repair enzyme, and PPP2R5C encodes the B56γ subunit of the PP2A tumour suppressor." (PMID 38443389, 2024). "We performed multivariate Cox proportional hazard (PH) analysis, adjusting for clinical variables that are significantly correlated with OS or PFS as a single variable (tumor grade, MGMT methylation status, and number of recurrences)." (PMID 38719809, 2024). "The GS model also outperformed established clinical prognostic factors, including neoplasm grade, IDH1 mutation status, and MGMT promoter methylation, as indicated by higher area-under-the-curve (AUC) values in ROC curves." (PMID 38819225, 2024). "This analysis incorporated information regarding tumor grade, age, sex, 1p/19q co-deletion status, IDH1 mutation status, MGMT methylation status, and risk score." (PMID 39574472, 2024). "In the case of patient ID40, who underwent complete resection of an unmethylated MGMT GB tumor, sEV-DNA methylation in the baseline sample was detected." (PMID 38762534, 2024). "The difficulty of acquiring tumor tissue for MGMT testing drives the need for non-invasive methods to predict MGMT status." (PMID 38612892, 2024). "We also noted a reduction in tumor stem cell characteristics, accompanied by an increase in H3K9ac, SP1, and MGMT levels, underscoring the potential role of H3K9ac in tumor relapse following TMZ therapy." (PMID 38448295, 2024).